RNU6-161P (RNA, U6 small nuclear 161, pseudogene)
Gene: Small nuclear RNA gene on chromosome 1 (76,753,135 to 76,753,240, forward strand). Ensembl gene ENSG00000199921.
Homologues: Orthologues: chimpanzee U6 (97% identical), macaque U6 (92% identical), dog U6 (69% identical), guinea pig U6 (62% identical). Paralogues in human: RNU6-1209P (88% identical), RNU6-1316P (86% identical), RNU6-797P (86% identical), RNU6-1031P (85% identical), RNU6-1145P (85% identical), RNU6-183P (85% identical), RNU6-29P (85% identical), RNU6-38P (85% identical), RNU6-742P (85% identical), RNU6-854P (85% identical), RNU6-1084P (84% identical), RNU6-1091P (84% identical), and 1287 more.